ACTL7B (actin like 7B)
Synonyms: Tact1
Tractability: No criterion of Open Targets' tractability assessment is met for any kind of drug.
Gene: Protein-coding gene on chromosome 9 (108,854,588 to 108,855,986, reverse strand). Ensembl gene ENSG00000148156.
Subcellular location: Cytoplasm, cytoskeleton
Gene Ontology:
Molecular function: protein binding; structural constituent of cytoskeleton; structural molecule activity
Biological process: cytoskeleton organization
Cellular component: actin cytoskeleton; cytoplasm; nucleus; cytoskeleton
Genetic constraint (gnomAD): Loss-of-function variants: 20 observed, 20.55 expected, observed/expected ratio (o/e) 0.97, 90% interval 0.68 to 1.41. The upper end of that interval is the gene's LOEUF score, 1.41, which puts it in group 5 of 6, group 1 being the genes least tolerant of losing a copy. Missense variants: 599 observed, 559.49 expected, observed/expected ratio (o/e) 1.07, 90% interval 1 to 1.14. Synonymous variants: 267 observed, 246.43 expected, observed/expected ratio (o/e) 1.08, 90% interval 0.98 to 1.2.
Homologues: Orthologues: chimpanzee ACTL7B (99% identical), macaque ACTL7B (98% identical), pig ACTL7B (90% identical), rabbit ACTL7B (88% identical), rat Actl7b (88% identical), mouse Actl7b (87% identical), guinea pig ACTL7B (83% identical), dog ACTL7B (75% identical). Paralogues in human: ACTL7A (56% identical), ACTG1 (40% identical), ACTB (40% identical), ACTA2 (39% identical), ACTG2 (39% identical), ACTC1 (39% identical), ACTA1 (38% identical), ACTBL2 (38% identical), ACTL9 (38% identical), ACTR1B (34% identical), ACTRT2 (33% identical), ACTR1A (33% identical), and 14 more.
Diseases named in the same sentence as ACTL7B in open-access papers:
ACTL7B is named in the same sentence as 10 diseases in open-access papers, as found by Europe PMC text mining. Sharing a sentence is not in itself a finding about the gene and the disease. The quoted sentences say what the papers report.
Azoospermia (1 paper, 2023). Absence of any measurable level of sperm,whereby spermatozoa cannot be observed even after centrifugation of the semen pellet. "Finally, ACTL7B has been identified to convey a high discriminating power between obstructive and non-obstructive azoospermia subtypes, both at protein and transcript levels, suggesting ACTL7B as a screening marker." (PMID 37800308, 2023).
infertile (1 paper, 2023). "As the genes of human and mouse ACTL7B are highly similar, we can surmise that ACTL7B variants can lead to failed spermatogenesis and infertility in humans." (PMID 37800308, 2023). "Furthermore, single nucleotide polymorphisms in ACTL7B have been identified in cohorts of infertile individuals." (PMID 37800308, 2023). "Male Actl7b-null mice are infertile and show severe oligoteratozoospermia with malformations of the sperm tails and heads." (PMID 37800308, 2023). "Fertility analysis revealed that Actl7b+/− males produce similar litter sizes and pregnancy frequencies to Actl7b+/+ males, whereas Actl7b−/− males are infertile." (PMID 37800308, 2023). "Interestingly, five polymorphisms in ACTL7B (and six in ACTL7A) were detected in a cohort of Japanese infertile male individuals, suggesting that ACTL7B plays a role in fertility." (PMID 37800308, 2023). "Single nucleotide polymorphisms in the coding sequence of ACTL7B in infertile men have been reported; however, they have not been directly correlated to male infertility." (PMID 37800308, 2023).
male infertility (1 paper, 2023). The inability of the male to effect fertilization of an ovum after a specified period of unprotected intercourse. "Our data unequivocally establish that mutations in ACTL7B are directly related to male infertility, pressing for additional research in humans." (PMID 37800308, 2023). "Our study clearly shows that mutations in ACTL7B might be directly connected to male infertility, calling for further investigations in human." (PMID 37800308, 2023). "We show that, in line with published data, loss of ACTL7B led to male infertility in mice due to the absence of functional mature sperm." (PMID 37800308, 2023).
ACTL7B also shares sentences with these, for which no sentence is quoted: cancer (2 papers); anal carcinoma (1); Familial dysautonomia (1); hepatocellular carcinoma (1); liver disease (1); oligospermia (1); tumor (1).